GRN (granulin precursor)
Diseases named in the same sentence as GRN in open-access papers (continued):
Sharing a sentence is not in itself a finding about the gene and the disease.
dementia (continued). "We included 106 presymptomatic and 54 symptomatic carriers of a pathogenic mutation in GRN, C9orf72 or MAPT, and 70 healthy non-carriers participating in the Genetic Frontotemporal dementia Initiative (GENFI), all of whom had at least one CSF sample." (PMID 32273328, 2020). "MAPT, GRN and C9ORF72 pathogenic mutations are not uncommon in our population with different types of dementia (5.4%, 5/93)." (PMID 27632209, 2016). "To investigate this intriguing hypothesis, we analyzed rare coding variability in 6 Mendelian dementia genes (APP, PSEN1, PSEN2, GRN, MAPT, and PRNP), in 141 LOAD patients and 179 elderly controls, neuropathologically proven, from the UK." (PMID 25104557, 2014). "GWASs have shown that common noncoding variability in Mendelian dementia genes (APP, PSEN1, PSEN2, MAPT, GRN, and PRNP) does not influence susceptibility to AD." (PMID 25104557, 2014). "•We have used exome sequencing to investigate rare coding variability in Mendelian dementia genes (APP, PSEN1, PSEN2, GRN, MAPT, and PRNP) in a cohort composed of 141 late-onset sporadic Alzheimer's disease cases and 179 elderly controls, autopsy proven from the UK." (PMID 25104557, 2014). "A novel variant in GRN, p.C247Y and a known variant in PSEN1, p.R35Q were found in demented individuals with a non-AD CSF profile suggesting another type of dementia." (PMID 23990795, 2013). "Within the PiB PET group, two cases had a GRN mutation and presence of FTLD‐TDP at post mortem, and the remaining seven were sporadic cases (i.e., no family history of younger‐onset dementia), including one who came to autopsy and showed evidence of FTLD‐tau at post mortem." (PMID 40820228, 2025). "Thus, we screened 6 Mendelian dementia genes (APP, PSEN1, PSEN2, MAPT, GRN, and PRNP) aiming to establish whether rare coding variability in these genes is responsible for an appreciable portion of the LOAD risk." (PMID 25104557, 2014).
neuronal ceroid lipofuscinosis (88 papers, 2014 to 2026). "Loss-of-function mutations in the GRN gene have been described as causes of FTD or neuronal ceroid lipofuscinosis, acting in a dosage-dependent manner." (PMID 40722695, 2025). "Progranulin localizes to lysosomes and is necessary for maintaining lysosomal function, as people with mutations on both GRN alleles develop a lysosomal storage disorder, neuronal ceroid lipofuscinosis." (PMID 41178544, 2025). "Homozygous GRN mutations are exceedingly rare and cause neuronal ceroid lipofuscinosis 11, a lysosomal storage disease with onset in young adulthood, or an FTD syndrome with late-onset manifestations." (PMID 40234992, 2025). "Homozygous GRN variants can cause neuronal ceroid lipofuscinosis, a lysosomal storage disorder, suggesting that PGRN plays an essential role in lysosomal homeostasis." (PMID 38347588, 2024). "Progranulin is cleaved in the lysosome into functional granulins, and homozygous loss-of-function pathogenic variants in GRN cause the lysosomal storage disorder neuronal ceroid lipofuscinosis." (PMID 39321401, 2024). "Loss of function mutations in both GRN alleles cause the severe lysosomal storage disorder neuronal ceroid lipofuscinosis (NCL), characterised by enlarged lysosomes and accumulation of the auto-fluorescent material lipofuscin." (PMID 36967384, 2023). "GRN mutations are proposed to disrupt lysosomal homeostasis, and hypomyelination is common to many lysosomal storage diseases, including neuronal ceroid lipofuscinosis (NCL) caused by homozygous GRN mutations." (PMID 36967384, 2023). "Homozygous GRN mutations cause a complete loss of progranulin, leading to neuronal ceroid lipofuscinosis (NCL), a lysosomal storage disorder which shares some neuropathological features with GRN-associated FTLD." (PMID 36142612, 2022). "Homozygous or compound heterozygous mutations of the GRN gene cause CLN11 (ceroid lipofuscinosis neuronal), while the heterozygous variant of the same gene is associated with FTD." (PMID 35752680, 2022). "Rare homozygous GRN mutations mostly cause neuronal ceroid lipofuscinosis (NCL), a lysosomal storage disorder that shares some neuropathological features with FTLD caused by heterozygous GRN mutations." (PMID 36361641, 2022). "Occasionally both alleles of GRN are mutated, leading to the complete loss of PGRN mRNA and resulting in a lysosomal storage disorder called neuronal ceroid lipofuscinosis (NCL)." (PMID 35095393, 2021). "Homozygous loss-of-function mutation of both GRN alleles causes neuronal ceroid lipofuscinosis (NCL), a lysosomal storage disease in which lipofuscins aberrantly accumulate in the affected tissues." (PMID 34618685, 2021). "An homozygous-null GRN mutation carrier has been reported presenting a clinical phenotype similarity to the neuronal ceroid lipofuscinosis (NCL), a lysosomal storage disease." (PMID 34413330, 2021). "Rare homozygous mutations in GRN were shown to cause a juvenile onset lysosomal storage neurodegenerative disorder called neuronal ceroid lipofuscinosis (NCL)." (PMID 33384578, 2020). "Complete loss of PGRN due to homozygous GRN mutations was reported as a cause for neuronal ceroid lipofuscinosis (NCL) linking rare lysosomal impairment to neurodegeneration in FTLD." (PMID 31105517, 2019). "Homozygous GRN mutation carriers develop neuronal ceroid lipofuscinosis (NCL), an earlier-onset lysosomal storage disorder caused by severe lysosomal dysfunction." (PMID 29929528, 2018).
neuronal ceroid lipofuscinosis (continued). "Haploinsufficiency of progranulin (PGRN) due to mutations in the granulin (GRN) gene causes frontotemporal lobar degeneration (FTLD), and complete loss of PGRN leads to a lysosomal storage disorder, neuronal ceroid lipofuscinosis (NCL)." (PMID 28541286, 2017). "Recently, it has been shown that a complete GRN deficiency due to a homozygous GRN loss-of-function mutation causes the rare lysosomal storage disease neuronal ceroid lipofuscinosis." (PMID 26388768, 2015). "A pair of siblings suffering from neuronal ceroid lipofuscinosis (NCL) was found to have a homozygous mutation in GRN, and the same GRN mutation in the heterozygous state is known to cause FTD." (PMID 26358247, 2015). "A homozygous GRN mutation was reported in two siblings withadult-onset neuronal ceroid lipofuscinosis, showing that homozygous mutations inGRN lead to a completely different phenotype of heterozygousmutations." (PMID 29213965, 2015). "Furthermore, GRN mutant cells were associated with abnormal lysosomal functions and neuronal ceroid lipofuscinosis (NCL), characterized by reduced proteolysis and decreased expression of cathepsin D in cortical neurons." (PMID 41155255, 2025). "Besides, homozygous loss-of-function GRN mutation leads to a rare adult-onset form of neuronal ceroid lipofuscinosis (NCL)." (PMID 31775776, 2019). "Interestingly, patients carrying two mutant GRN alleles present with adolescent-onset neuronal ceroid lipofuscinosis (NCL), a lysosomal storage disorder." (PMID 31639062, 2019). "Heterozygous mutations in GRN, a lysosomal localized protein, cause FTD and lead to biochemical changes characteristic of lysosomal storage diseases; with rare homozygous GRN mutations directly causing neuronal ceroid lipofuscinosis, a lysosomal storage disorder." (PMID 30496365, 2018). "Progranulin deficiency due to heterozygous null mutations in the GRN gene are a common cause of familial frontotemporal lobar degeneration (FTLD), while homozygous loss-of-function GRN mutations are thought to be a rare cause of neuronal ceroid lipofuscinosis (NCL)." (PMID 29149899, 2017). "Furthermore, two patients with neuronal ceroid lipofuscinosis (NCL) have been reported to be homozygous for loss of function mutations in GRN (NCL/GRN)." (PMID 25785851, 2015). "People with loss-of-function mutations on both GRN alleles, resulting in complete progranulin deficiency, develop the lysosomal storage disorder Neuronal Ceroid Lipofuscinosis (NCL)." (PMID 38840181, 2024). "In humans, homozygous GRN gene mutations invariably lead to neuronal ceroid lipofuscinosis (NCL) with an age of onset <25 years with 100 percent penetrance." (PMID 37958929, 2023). "In rare cases, homozygous or complex heterozygous mutations in GRN cause complete progranulin deficiency, which results in a lysosomal storage disorder called neuronal ceroid lipofuscinosis (NCL)." (PMID 36781744, 2023). "Of note, homozygous GRN null mutations cause adult-onset neuronal ceroid lipofuscinosis (NCL), a lysosomal storage disorder." (PMID 34948429, 2021). "Exome sequencing of two Italian siblings with neuronal ceroid lipofuscinosis (NCL) revealed that homozygous loss of GRN caused the lysosomal storage disease." (PMID 34366786, 2021). "The presence of loss-of-function mutations on both GRN alleles, resulting in nearly complete progranulin deficiency, typically causes the lysosomal storage disorder neuronal ceroid lipofuscinosis (NCL)." (PMID 34298019, 2021). "For instance, while heterozygous mutations in GRN causes FTD, rare homozygous mutations in GRN have been found to cause neuronal ceroid lipofuscinosis (NCL), a lysosomal storage disorder." (PMID 30496365, 2018). "For instance, neuronal ceroid lipofuscinosis (NCL) has been linked to mutations of genes related to lysosomal function, including GRN (granulin), CTSD (cathepsin D) and CLN5 (ceroid lipofuscinosis neuronal protein 5)." (PMID 41387918, 2025).
neuronal ceroid lipofuscinosis (continued). "The complete loss of PGRN function, typically due to homozygous GRN mutations, causes neuronal ceroid lipofuscinosis (NCL, also known as Batten disease), a classical lysosomal storage disorder marked by the accumulation of ceroid lipofuscin." (PMID 40498021, 2025). "A single defunct GRN allele increases the risk of developing FTD, but two mutant alleles result in Neuronal Ceroid Lipofuscinosis (NCL-11), a lysosomal storage disorder (LSD)." (PMID 38037070, 2023). "Heterozygous mutations in GRN cause FTD, while homozygous mutations cause a lysosomal storage disorder named neuronal ceroid lipofuscinosis, suggesting that progranulin is involved in lysosomal biogenesis and homeostasis." (PMID 37628709, 2023). "However, the homozygous GRN mutations result in neuronal ceroid lipofuscinosis (NCL), a lysosomal storage disease." (PMID 35054815, 2022). "Heterozygous GRN mutations are linked to familial frontotemporal lobar degeneration (FTLD), whereas homozygous ones lead to the development of neuronal ceroid lipofuscinosis (NCL)." (PMID 35859258, 2022). "Rare homozygous GRN mutations mostly cause neuronal ceroid lipofuscinosis (NCL), a lysosomal storage disorder which shares some neuropathological features with GRN-FTLD." (PMID 35159297, 2022). "While heterozygous GRN mutations cause FTLD, homozygous GRN mutations cause neuronal ceroid lipofuscinosis (NCL), a lysosomal storage disorder, although a few homozygous cases have shown FTLD phenotype." (PMID 36430231, 2022). "One form of the LSD neuronal ceroid lipofuscinosis (NCL), known as Batten disease, is caused by homozygous mutations in the GRN gene, which encodes progranulin (PGRN), a lysosomal glycoprotein." (PMID 34757540, 2022). "Indeed, homozygous carriers of GRN mutations develop young adult-onset neuronal ceroid lipofuscinosis (NCL), a lysosomal storage disease characterized by lipofuscin deposition." (PMID 33802612, 2021). "FTD-GRN is caused by heterozygous mutations, while individuals homozygous for pathogenic GRN mutations develop neuronal ceroid lipofuscinosis instead of FTD, making Grn+/− mice a closer genetic model of human FTD-GRN than Grn−/− mice." (PMID 29929528, 2018). "Loss of function mutations in granulin (GRN) are linked to two distinct neurological disorders, frontotemporal lobar degeneration (FTLD) and neuronal ceroid lipofuscinosis (NCL)." (PMID 25785851, 2015). "While PGRN haploinsufficiency causes FTLD-TDP, complete loss of function of PGRN due to homozygous GRN mutations leads to neuronal ceroid lipofuscinosis (CLN11), a rare lysosomal storage disorder characterized by excessive accumulation of lipofuscins in the lysosome." (PMID 40713630, 2025). "Moreover, mutations in the human GRN gene are associated with early onset of age-related neurodegenerative diseases, such as frontotemporal lobar degeneration (FTLD) and neuronal ceroid lipofuscinosis (NCL)." (PMID 32028681, 2020). "Mutation in the GRN gene, encoding the progranulin (PGRN) protein, shows a dose-dependent disease correlation, wherein haploinsufficiency results in frontotemporal lobar degeneration (FTLD) and complete loss results in neuronal ceroid lipofuscinosis (NCL)." (PMID 31291241, 2019). "With the respect to the GRN gene, a partial loss of function causes FTLD with ubiquitinated TAR DNA-binding protein-43-positive inclusions, while the complete loss of function develops neuronal ceroid lipofuscinosis." (PMID 25478031, 2014). "Individuals null for GRN typically suffer from a rare form of neuronal ceroid lipofuscinosis (NCL), CLN11, with disease onset ranging from teenage years to midlife." (PMID 33795008, 2021). "Interestingly, a GRN loss-of-function, caused by a homozygous 4-bp deletion in the GRN gene has been associated with NCL11, a form of neuronal ceroid lipofuscinosis, in which the lysosomal storage disorder coexists with the accumulation of phosphorylated TDP-43 in neurons." (PMID 27193329, 2016).
neuronal ceroid lipofuscinosis (continued). "Loss of function, mutation of the human GRN gene, and insufficient haploidy of PGRN may potentially affect PGRN levels, leading to neurodegenerative diseases such as frontotemporal degeneration (FTLD), neuronal ceroid lipofuscinosis, and Alzheimer’s disease." (PMID 40290306, 2025). "Indeed, homozygous deletion of GRN does not lead to FTLD-TDP but to another disorder called Neuronal Ceroid Lipofuscinosis (NCL) which is characterized by lysosomal dysfunction." (PMID 27435172, 2016).
Alzheimer disease (78 papers, 2011 to 2026). A progressive, neurodegenerative disease characterized by loss of function and death of nerve cells in several areas of the brain leading to loss of cognitive function such as memory and language. "As well as FTD and LSDs, specific GRN variants have also been implicated in both Alzheimer’s Disease (AD) and Parkinson’s Disease (PD)." (PMID 40200337, 2025). "Polymorphisms in the GRN gene also contribute to the risk of Alzheimer’s disease (AD), and GRN is closely linked to Parkinson’s disease (PD)." (PMID 40528203, 2025). "GRN gene variants are also known to increase the risk of developing Alzheimer’s disease (AD) and PD43." (PMID 38890280, 2024). "Variation at the GRN locus is also associated with Alzheimer’s disease and limbic-predominant age-associated TDP-43 encephalopathy (LATE)." (PMID 36781744, 2023). "A repurposed genome-wide association study (GWAS) of late-onset Alzheimer’s Dementia, revealed two SNPs on chromosome 1 linked to lower plasma GRN levels." (PMID 34366786, 2021). "The GRN rs5848 polymorphism was reported in Alzheimer’s Disease (AD) and Parkinson’s Disease (PD) patients as risk factor for ubiquitin- and TDP-43 -positive frontotemporal degeneration." (PMID 34946792, 2021). "Regarding Alzheimer’s disease biomarkers, of our cohort of GRN mutation carriers, 21 patients have had collected CSF Alzheimer’s disease biomarkers." (PMID 33216842, 2020). "The neuropsychological and imaging data place GRN mutation carriers in an intermediate position between Alzheimer’s disease and FTD." (PMID 33216842, 2020). "In our cohort, GRN mutation carriers have worse scores in executive functions, initiative and psychomotor control than both Alzheimer’s disease and behavioural-variant frontotemporal dementia (bvFTD) patients matched for age, severity and education." (PMID 33216842, 2020). "Although asymmetry is common in the Alzheimer’s disease cases we reported, the less involved contralateral hemisphere was rarely spared to the degree that it is in GRN mutation carriers." (PMID 33216830, 2020). "Two of the patients who carried both the GRN mutation and p.A152T also had Alzheimer’s disease co-pathology." (PMID 28594853, 2017). "Further, GRN variants that decrease PGRN expression increase the risk of developing Alzheimer’s disease (AD) and Parkinson’s disease (PD)." (PMID 27341800, 2016). "Remarkably, genetic variation in GRN has also been linked to other late onset neurodegenerative diseases such as Alzheimer's disease." (PMID 26869920, 2016). "GRN polymorphisms are associated with increased risk for Alzheimer's disease and Parkinson's disease, and may also influence cognitive aging." (PMID 41178544, 2025). "Additionally, we have observed a robust association between the GRN protein and Alzheimer’s disease, validating the discovery and replication phases of MR analysis, with colocalization evidence supporting both phases." (PMID 38820305, 2024). "Alzheimer’s disease clinical trials have indicated that disease-modifying therapies are more effective when delivered early, and, in theory, treatment of GRN mutation carriers could be initiated early in life." (PMID 36781744, 2023). "GRN: risk factor for clinical early-onset Alzheimer’s disease?" (PMID 35393555, 2022). "GRN emerged as a particular promising target from our analyses since it was prioritised in our main MR analysis for Parkinson’s disease, but also showed a suggestive relationship with Alzheimer’s disease risk." (PMID 33417599, 2021). "Certain GRN variants may also increase the risk for Alzheimer's disease (AD), yet associations could not be confirmed in some other studies." (PMID 30482868, 2018). "GRN gene mutations were found to cause frontotemporal dementia and have been associated with other neurodegenerative diseases, such as Parkinson’s disease, Creutzfeldt-Jakob disease, motor neuron disease, and Alzheimer’s disease." (PMID 26408020, 2015).